LGALS3 (galectin 3)
Diseases named in the same sentence as LGALS3 in open-access papers (continued):
Sharing a sentence is not in itself a finding about the gene and the disease.
left ventricular hypertrophy (11 papers, 2011 to 2025). Enlargement of the LEFT VENTRICLE of the heart. "Increasing serum galectin-3 values were also associated with left ventricular hypertrophy, positively correlating with left ventricular mass index (r: 0.812, p-value < 0.001) and relative wall thickness (r: 0.318, p-value < 0.001)." (PMID 38519721, 2024). "Serum galectin-3 levels in cats according to the characteristics of cats with left ventricular hypertrophy." (PMID 39619937, 2024). "Serum galectin-3 was related to left atrial enlargement and left ventricular hypertrophy, suggesting a relationship with cardiac structural remodeling." (PMID 35039576, 2022). "A rat model of HF revealed that galectin-3 is the strongest regulated gene when compensated left ventricular hypertrophy was compared with overt HF." (PMID 21189092, 2011).
metastatic melanoma (11 papers, 2010 to 2025). A melanoma that has spread from its primary site to another anatomic site. "In metastatic melanoma and head and neck cancers, anti-PD-1 treatments are improved by belapectin (GR-MD-02), a galectin-3 inhibitor." (PMID 34572756, 2021).
pancreatitis (11 papers, 2012 to 2025). Inflammation of the pancreas. "The most probable reason for the heterogeneous diagnostic performance of galectin-3 may be inconsistency in the control groups (healthy volunteer or pancreatitis patients)." (PMID 31832021, 2019). "IgG4-related pancreatitis samples (n = 5) showed a 3-fold up-regulation of LGALS-3 expression compared with healthy pancreas (n = 4)." (PMID 28593065, 2017). "We selected galectin-3, as it was one of the highly upregulated proteins in IgG4-related pancreatitis (13-fold, P value 0.013)." (PMID 28593065, 2017). "Immunoblotting showed that galectin-3 protein levels in the same samples as qRT-PCR were 5.1-fold higher in IgG4-related pancreatitis samples than that of normal pancreas." (PMID 28593065, 2017). "Finally, information on various factors that are associated with raised galectin-3 levels, such as fibrotic conditions of other organs, including the liver, lung, pancreatitis, and the kidneys, was not fully available to investigators." (PMID 40747494, 2025). "We chose the protein galectin-3, identified by LC-MS with high confidence and differential expression in FFPE samples of IgG4-related pancreatitis tissues." (PMID 28593065, 2017).
Candida infection (10 papers, 2017 to 2021). "Galectin-3 deficiency ameliorates systemic candidiasis by reducing fungal burden, renal pathology, and mortality." (PMID 28217127, 2017). "The S-type lectin receptor Galectin-3 is expressed on neutrophils, monocytes, macrophages, endothelial cells, and epithelial cells, can be secreted, and confers protection in Candida infection leaving galectin-3-deficient mice more susceptible to Candida infection." (PMID 28360910, 2017). "SjS patients have been shown to have significantly higher serum levels of galectin-3, which plays a possibly active role in host defense against Candida infection." (PMID 35127751, 2021). "Adoptive transfer experiments demonstrate that cell intrinsic galectin-3 negatively regulates neutrophil effector functions against candidiasis." (PMID 28217127, 2017). "Our work unravels the mechanism by which galectin-3 regulates Syk-dependent neutrophil fungicidal functions and raises the possibility that blocking gal3 in neutrophils may be a promising therapeutic strategy for treating systemic candidiasis." (PMID 28217127, 2017). "CLRs, such as Dectin-1 and DC-SIGN; TLRs, such as TLR2 and TLR4; and other receptors such as Galectin-3 and CR3 have all been shown to play a role in Candida infection." (PMID 33562068, 2021).
congenital heart disease (10 papers, 2020 to 2025). A heart disease that is present at birth. "There are limited data on serum galectin-3 levels in children and most studies have been conducted on congenital heart diseases." (PMID 37715793, 2023). "Although the study was conducted on a small sample size (only 16 patients), these results raise doubt of whether galectin-3 may be a useful marker of myocardial damage of the right ventricle in patients after correction of congenital heart diseases." (PMID 35410028, 2022). "Moreover, the authors found a correlation between galectin-3 and global longitudinal strain in adults with congenital heart diseases." (PMID 35410028, 2022). "Galectin-3 is a strong predictor of poor prognosis in the early follow up after surgery in children treated for such congenital heart diseases as a ventricular septal defect, atrioventricular septal defect or pulmonary valve regurgitation after tetralogy of Fallot repair." (PMID 35410028, 2022). "Galectin-3 was also broadly studied in grown-ups with congenital heart diseases, and the results could serve as a direction for future research in younger cohorts." (PMID 35410028, 2022). "Backround and Objective: We sought to assess in adult congenital heart disease (ACHD) patients the prognostic value of plasma galectin-3 (Gal-3) levels and systemic ventricular global longitudinal strain (SV GLS) as well as their association with NTproBNP and arrhythmogenesis." (PMID 32580463, 2020).
inflammatory bowel disease (10 papers, 2012 to 2025). A spectrum of small and large bowel inflammatory diseases of unknown etiology. "Nrf2 and galectin-3 (Gal-3) represent two mechanistically distinct biomarker families that capture different pathogenic dimensions of inflammatory bowel disease." (PMID 41462607, 2025). "Downregulation of galectin-3 was demonstrated in inflamed intestinal mucosa of patients with inflammatory bowel disease, but elevated serum levels are present in patients with ulcerative colitis and Crohn’s disease." (PMID 41373557, 2025). "Fecal galectin-3 levels have the potential to become a non-invasive biomarker for the diagnosis and prognosis of inflammatory bowel diseases." (PMID 37189804, 2023). "Serum levels of galectin-3 have been used to monitor the inflammatory stage of inflammatory bowel disease." (PMID 25033447, 2014). "Galectin-3, an inflammatory and fibrotic molecule, has elevated circulating levels in patients with chronic liver disease and inflammatory bowel disease (IBD)." (PMID 38731984, 2024).
influenza (10 papers, 2020 to 2024). An acute viral infection of the respiratory tract, occurring in isolated cases, in epidemics, or in pandemics; it is caused by serologically different strains of viruses (influenzaviruses) designated A, B, and C, has a 3-day incubation period, and usually lasts for 3 to 10 days. "While galectin-3 expression was significantly upregulated in mice and humans with IPA, LGALS3 transcript levels were instead lower in BAL from patients with IAPA compared to those with influenza alone." (PMID 38651925, 2024). "More importantly, our findings identify galectin-3 as a potential target for developing anti-influenza drugs." (PMID 36823664, 2023). "We used galectin-3 knockout and wild-type mice and cells to study the intracellular role of galectin-3 in influenza pathogenesis." (PMID 36823664, 2023). "Our results also suggest that inhibition of galectin-3 may be a potential therapeutic strategy for influenza." (PMID 36823664, 2023). "Galectin-3 promotes neutrophil migration towards infection sites via binding to specific glycan structures on their surface and recruiting neutrophils to the lungs during influenza and Streptococcus pneumoniae co-infection." (PMID 37298569, 2023). "Furthermore, our findings provide potential therapeutic interventions and suggest galectin-3 as a potential therapeutic target for influenza." (PMID 36823664, 2023). "Our findings identify galectin-3 as a novel target for the development of anti-influenza drugs." (PMID 36823664, 2023). "Our findings also identify galectin-3 as a potential therapeutic target for influenza." (PMID 36823664, 2023). "Furthermore, a study with a mouse model of pneumococcal pneumonia after influenza has shown that galectin-1 and, in particular, galectin-3 expressed and secreted in the airway epithelial cells upon IAV infection bind strongly to IAV and Streptococcus pneumoniae." (PMID 36823664, 2023). "Galectin-3 has been identified as a crucial mediator in the entry and attachment of herpes simplex virus (HSV) during ocular infections and facilitating influenza binding to airway epithelial cells." (PMID 37298569, 2023).
nonalcoholic fatty liver disease (10 papers, 2012 to 2024). "Some studies have shown that galectin-3 deficiency in male mice can spontaneously develop non-alcoholic fatty liver disease and more severe hepatic injury." (PMID 34778306, 2021).
ulcerative colitis (10 papers, 2019 to 2025). An inflammatory bowel disease involving the mucosal surface of the large intestine and rectum. "Protein-protein interaction analysis has underscored the significance of hub genes, notably Stat3, Il1b, Mmp3, and Lgals3, in the progression of ulcerative colitis." (PMID 38308210, 2024). "Elevated fecal galectin-3 levels (>553.44 pg/mL) were an indicator of the attenuation of ulcerative colitis." (PMID 37189804, 2023). "We investigated molecular mechanisms responsible for the Galectin-3-dependent regulation of colon inflammation and evaluated whether Galectin-3 may be used as biomarker for monitoring the progression of ulcerative colitis (UC)." (PMID 31336879, 2019). "A negative correlation between CXCL11 and galectin-3 has previously been found in serum from individuals with ulcerative colitis." (PMID 39044165, 2024). "Fecal galectin-3 levels of patients with ulcerative colitis and metabolic syndrome were ~3-fold higher compared to those of ulcerative colitis patients not suffering from metabolic dysfunction." (PMID 37189804, 2023).
allergic asthma (9 papers, 2011 to 2025). A asthma with a basis in a pathological type I hypersensitivity reaction. "Galectin-3, on the other hand, appears to have a pro-inflammatory role in allergic asthma, as a study in mice showed that galectin-3 expressing inflammatory cells were recruited to the lungs upon allergen exposure." (PMID 40636105, 2025). "Finally, two proteins were identified as more closely related to non-allergic asthma according to specificity analysis, namely IL-25 and LGALS3." (PMID 33936056, 2021). "Finally, two proteins (IL-25 and LGALS3) were identified as being more related to non-allergic asthma according to the specificity analysis performed." (PMID 33936056, 2021). "We observed a significant increase in galectin-3 (Gal-3), interleukin-17 (IL-17), and transforming growth factor-β1 (TGF-β1) gene expression in lung tissue isolated from an allergic asthma murine model utilizing TIMPKO." (PMID 34221020, 2021). "Moreover, LGALS3 was the only one to display a stronger overall relationship with nonallergic than with allergic asthma." (PMID 33936056, 2021). "Moreover, LGALS3 or Galectin-3 was the only protein to display a higher general relationship with nonallergic than with allergic asthma." (PMID 33936056, 2021).
Anxiety (9 papers, 2012 to 2025). Intense feelings of nervousness, tension, or panic often arise in response to interpersonal stresses. "The main finding of this post-hoc analysis from the Diast-CHF study is that, in a cohort of patients with cardiovascular risk factors, the plasma concentration of galectin-3 is inversely correlated with self-assessed anxiety." (PMID 33024450, 2020). "Most recently we evaluated the role of Galectin-3 deficiency on anxiety levels in C57Bl/6 mice, under physiological conditions, as well as following acute LPS-induced neuroinflammation." (PMID 32455781, 2020). "However, possible associations of galectin-3 with emotional well-being in general, and anxiety in particular, are unclear." (PMID 33024450, 2020). "In line, we observed in our study population that decreased circulating galectin-3 concentrations are linked to higher levels of anxiety, which may in turn have resulted from a chronically elevated psychological stress level." (PMID 33024450, 2020). "The anti-inflammatory effects of cortisol usually associated with increased stress levels and anxiety may have an overall suppressive effect on the synthesis and subsequent release of galectin-3 in the circulation." (PMID 33024450, 2020). "The association between galectin-3 and HADS anxiety is weak and remains stable in multivariate models adjusted to clinically relevant confounders." (PMID 33024450, 2020). "On the other hand, the final conclusion considering the anxiety level control influenced by Galectin-3 is crucially affected by the existence of inflammation in the targeted tissue." (PMID 32455781, 2020). "Data showed that, also in this model, galectin-3 was a significant and independent predictor for anxiety (B = -2.413, 95%CI = -4.422–-0.404, p = 0.019) (model 2)." (PMID 33024450, 2020). "The major finding was the observation of the two contradictory effects of Galectin-3 on anxiety level depending on the animals’ preconditioning." (PMID 32455781, 2020). "In our remyelination studies, a decrease in anxiety persisted both in WT and LGALS3-/- mice after 2-week recovery, as evidenced by higher rates of entries and more time spent in open arms in the plus maze test." (PMID 30258354, 2018). "In this line, work by our group has shown diminished anxiety behavior in LGALS3-/- mice, similar to that observed in early CPZ-induced demyelination." (PMID 30258354, 2018). "In a linear regression model adjusted for gender, age, BMI, eGFR, LVEF, ASE grade, 6-min walking test, and SF-36 physical functioning, we found that log-transformed galectin-3 concentrations independently predicted HADS anxiety (B = -2.493, 95%CI = -4.354–-0.632, p = 0.009) (model 1)." (PMID 33024450, 2020). "Future research will have to show whether indeed galectin-3 may attenuate anxiety-related responses and thus protects the heart from the adverse cardiac effects of psychosocial stress." (PMID 33024450, 2020). "In patients with cardiovascular risk factors, serum galectin-3 is linked to anxiety and this relationship is independent of physical impairment and serum concentrations of natriuretic peptides." (PMID 33024450, 2020). "Furthermore, LGALS3-/- mice exhibited substantial alterations in behavior with diminished levels of innate anxiety than their WT littermates." (PMID 30258354, 2018). "It is thought that other factors besides galectin-3 may also contribute to retention performance; accordingly, we measured the shock sensitivity, locomotor activity, and the anxiety state of these mice." (PMID 28744198, 2017). "Our data demonstrate that, independently of natriuretic peptides and the biomarker CT-proAVP, higher levels of circulating galectin-3 predict less anxiety, suggesting that the β-galactoside-binding protein galectin-3 may modulate neuronal pathways engaged in the regulation of anxiety." (PMID 33024450, 2020).
Anxiety (continued). "Finally, we tested whether the inverse and significant association between galectin-3 and HADS anxiety remained stable, when additionally NT-proBNP, MR-proANP and CT-proAVP were included as confounders in the model." (PMID 33024450, 2020). "C57BL6 galectin-3−/− mice <90 days of age also performed identically to controls on locomotor, hole-board, or inverted screen tests in another recent study; however, they displayed an increased percentage of open arm entries in a plus-maze test, suggesting reduced anxiety." (PMID 23139902, 2012). "In univariate analysis, there was a weak but significant inverse correlation between galectin-3 and HADS anxiety (rho = − 0.076; p = 0.008)." (PMID 33024450, 2020). "However, in humans, specific associations of galectin-3 with anxiety have not been studied so far." (PMID 33024450, 2020). "However, our cross-sectional data do not prove a causal effect of galectin-3 on anxiety." (PMID 33024450, 2020). "This relationship between galectin-3 and HADS anxiety was weak but remained stable when, in a multivariate model, clinical variables indicative of physical impairment were added as putative confounders." (PMID 33024450, 2020). "There was also a significant negative correlation of galectin-3 with HADS anxiety (rho = -0.076, p = 0.008) and eGFR (rho = -0.063, p = 0.032), respectively." (PMID 33024450, 2020). "Higher anxiety might also lead to suppressed production and/or release of galectin-3 or both could depend on an unknown third factor not identified in our analyses." (PMID 33024450, 2020). "Thus, our main finding of an inverse relationship between self-rated anxiety and galectin-3 secretion into the circulation may not be completely unexpected." (PMID 33024450, 2020). "Accordingly, the lack of Gal-3 and alterations in myelin structure in LGALS3-/- mice induces behavioral alterations such as lower anxiety levels and spatial working memory impairment." (PMID 30258354, 2018).